RNU6-257P (RNA, U6 small nuclear 257, pseudogene)
Gene: Small nuclear RNA gene on chromosome 16 (48,731,704 to 48,731,801, reverse strand). Ensembl gene ENSG00000222170.
Homologues: Orthologues: chimpanzee U6 (98% identical), macaque U6 (83% identical), pig U6 (80% identical), guinea pig U6 (70% identical), rat U6 (67% identical), dog U6 (58% identical). Paralogues in human: RNU6-1005P (84% identical), RNU6-1011P (84% identical), RNU6-16P (84% identical), RNU6-38P (84% identical), RNU6-434P (84% identical), RNU6-820P (84% identical), RNU6-1013P (83% identical), RNU6-266P (83% identical), RNU6-480P (83% identical), RNU6-737P (83% identical), RNU6-869P (83% identical), RNU6-1145P (82% identical), and 1286 more.